MTND6P33 (MT-ND6 pseudogene 33)
Gene: Unprocessed pseudogene on chromosome 16 (10,719,833 to 10,720,015, forward strand). Ensembl gene ENSG00000262107.
Diseases named in the same sentence as MTND6P33 in open-access papers:
MTND6P33 is named in the same sentence as 1 disease in open-access papers, as found by Europe PMC text mining. Sharing a sentence is not in itself a finding about the gene and the disease. The quoted sentences say what the papers report.
glioblastoma (1 paper, 2023). The most malignant astrocytic tumor (WHO grade IV). "Two genes, MTND6P33 and RNU1-2, were specific to glioblastoma patients with TERT promoter mutations and MGMT methylation." (PMID 37568598, 2023).